CD4 (CD4 molecule)
Diseases named in the same sentence as CD4 in open-access papers (continued):
Sharing a sentence is not in itself a finding about the gene and the disease.
tumor (continued). "Expression of IDO1 was not dose dependent and there was no significant increase in the CD8+ or CD4+ effector T cells or tumour-infiltrating leucocytes." (PMID 37041200, 2023). "HIV+ samples had higher PD-L1 expression rates in tumour tissue (51% vs. 8% p <0.0001) and displayed denser intratumoural CD4+/FOXP3+ (p <0.0001), CD8+/PD1+ (p <0.0001), with lower total peritumoural CD4+ (p <0.0001) and higher peritumoural CD8+/PD1+ (p <0.0001)." (PMID 37274775, 2023). "The establishment of this eminently proinflammatory milieu was succeeded by a depletion of lymphocytes with the immunosuppressive phenotype of regulatory T cells (TRegs; CD4+ CD25+ Foxp3+) and, ultimately, by increases in the presentation of tumor antigens by CD11b+ cells." (PMID 37947651, 2023). "CD8+ T cell depletion also impacted tumor growth, albeit not to the magnitude of CD4+ T cell depletion." (PMID 36881480, 2023). "Strikingly, the anti-tumor activity of cGAMP in mouse colon cancer and melanoma was impaired in the absence of CD4 T cell-derived IL-9 or IFNγ." (PMID 37189417, 2023). "Tregs make up 10% of all CD4+ T lymphocytes in the peripheral blood of healthy people, rising up to 30–50% in the presence of tumor lesions, inhibiting the activation of CD8+ T and CD4+ T lymphocytes and hence, playing an essential role in immunosuppression and angiogenesis." (PMID 37108109, 2023). "Although data on cytolytic anti-tumor activity of the transferred CD4+ T cells was not provided, release of the effector cytokine IFNγ was demonstrated." (PMID 37965314, 2023). "Moreover, SC144@HABN + anti-PD-L1 combo therapy significantly decreased the frequency of CD4+FoxP3+ regulatory T-cells and CD45-PD-L1+ tumor cells in the TME, compared with other groups." (PMID 37553327, 2023). "Therefore, strengthening immune activity through engineering modification of CD4+ T cells and CD8+ T cell-derived exosomes is a novel strategy to improve the efficacy of tumor immunotherapy." (PMID 37153615, 2023). "Hence, similar to the kinetics of CD4+ TIL infiltration, MC38 tumours are increasingly infiltrated by CD8+ effectors during progressive tumour outgrowth." (PMID 37153625, 2023). "Moreover, the percentage of CD3+, CD4+ and CD8+ T cells in the blood increased after cryo-thermal therapy compared with those in the tumor-bearing control." (PMID 37108179, 2023). "The results show that there is a significant relationship between LRHG and the degree of immune cell infiltration in the tumor in T cells CD8, T cells CD4 memory activated, T cells follicular helper, monocytes, T cells gamma delta, macrophages M1 and eosinophils, especially in T cells." (PMID 37741901, 2023). "A study showed that oral FAP-DNA vaccine could induce both CD8+ and CD4+ immune responses, and antitumor immunity was enhanced by combing FAP DNA vaccine with other tumor antigen-specific DNA vaccines." (PMID 37064113, 2023). "Importantly, the number of CD4+ and CD8+ cells was significantly higher in the tumor-draining lymph nodes in AhR-silenced-MOC1-implanted mice." (PMID 37830596, 2023). "Therefore, we assessed the effect of combination treatment on T-helper lymphocytes (CD4+), cytotoxic lymphocytes (CD8+), activated lymphocytes (Granzyme B+), and antitumor macrophages (CD86 positive M1 type macrophages) infiltrating tumor tissue." (PMID 37640735, 2023). "In fact, given our earlier work demonstrating that NAE inhibition suppressed expansion of Treg cells and increased CD4+ T-cell polarization towards TH1 phenotype in vitro and in ova-stimulation model in vivo, CD4+ T cells likely significantly contribute to anti-tumor effect." (PMID 37031300, 2023). "Interestingly, the NLRP3 inflammasome expression is negatively correlated to the number of effective CD4+ and CD8+ T cells that exert effects on anti-tumor immunity." (PMID 37705746, 2023).
tumor (continued). "Among the T cells, both the CD4+ and CD8+ subpopulations were ~10-fold larger, while the percentage of CD4+Foxp3+ T regulatory (Treg) cells, which are negative regulators of antitumour immunity, was much smaller in tumours from TIOs+NIR3-treated mice." (PMID 37673934, 2023). "CD96 co-expression with CD226 was also significantly more frequent in cells from the blood than from the tumour (>3-fold mean difference in all subsets) and rare in tumours (Highest mean frequency of 7.3% ±1.4% in non-Treg CD4 + T cells)." (PMID 37596248, 2023). "Single-cell RNA sequencing and mass cytometry expose systemic and dynamic activation states of therapy-responsive CD4+ and CD8+ T cells in tumor-bearing mice with expression of distinct natural killer (NK) cell receptors, granzymes, and chemokines/chemokine receptors." (PMID 36796366, 2023). "Similar to curcumin (Cur), CA-1 has the characteristics of inducing tumor death through chemotherapy to enhance tumor immunogenicity, and effectively recruit CD4+T helper cells (Th) and CD8+ cytotoxic T lymphocytes (CTL) for the enhancement of anti-tumor immune responses." (PMID 37153576, 2023). "CD4 depletion at tumor implantation did not affect the proportion of antigen-specific T cells in the tumor, or the proportion that express CD103." (PMID 37072485, 2023). "We have obtained a predictive model for TNM which combines peripheral blood parameters (% CD27+ CD4+ lymphocytes, % IDO+ monocytes, LAG3 MFI in CD4+ lymphocytes) with histological grade and tumor size and discriminates pTa and pT1 tumors with a sensitivity of 75% and specificity of 96.65%." (PMID 36900156, 2023). "Furthermore, As-T combination therapy also significantly reduced the amount of CD223+ and CD279+ on intra-tumor CD8+T cells, and CD4+FOXP3+ Treg cells." (PMID 38161697, 2023). "With regard to the role of these neo-Ag specific CD4+ T cells in anti-tumor immunity, it has not been explained completely." (PMID 35269735, 2022). "Effector CD4+ and CD8+ T cell numbers increased within the TME leading to tumor elimination." (PMID 36551637, 2022). "CD4 and CD8 T cells have a dual role in effective anti-tumor responses." (PMID 35565329, 2022). "Because the discovery of adaptive immune responses against cancer and IFN-γ–mediated tumor rejection, the field has overwhelmingly characterized CD8+ cytotoxic T lymphocytes (CTLs) and CD4+ Th1 cells, both of which produce IFN-γ, as T-cell subsets that mediate anti-tumor immunity." (PMID 36248881, 2022). "The cDC1 subset excel at cross‐presentation of exogenous microbial and tumour antigens to efficiently prime CD8+ T cells and activate CD4+ T cells through MHC class II antigen (MHCII) presentation resulting in the polarization of activated CD4+ T cells towards a Th1 phenotype." (PMID 34767637, 2022). "Moreover, there are reports of tumor-specific phosphorylated peptides stimulating CD8 and CD4 T cells and even phosphopeptide-specific T cells in cancer." (PMID 36291752, 2022). "Interestingly, in this study, positive correlations among CLST, CD4+TLR-NL, CD4+TEM-TH1/TH17, and ICs indicated their crosstalk in the tumor tissue of HBV-HCC." (PMID 36569318, 2022). "The results showed that high CBPscores are companied with pro-tumor immune infiltrations including M2 macrophages and resting mast cells, and samples with low CBPscores had more anti-tumor immune infiltrations (CD8 T cells, plasma cells, memory activated CD4 T cells and follicular helper T cells)." (PMID 36291668, 2022). "Bispecific TCEs can redirect both CD4+ as well as CD8+ T cells for the killing of tumor cells and are independent of intrinsic antigen-specific T cell receptor recognition by the T cells." (PMID 36509287, 2022). "In addition, we evaluated the distribution of CD4+ TRM cells and CD8+ TRM cells in the tumor tissue and found that the proportion of TRM within TLSs was significantly higher than that outside, especially CD4+ TRM." (PMID 35663939, 2022).
tumor (continued). "High tumor telomerase activity is a well-established negative prognostic factor across multiple cancer indications, whereas anti-telomerase CD4 T cell immune responses are emerging as independent positive prognostic factors validated in several malignancies." (PMID 36089578, 2022). "This immunogenic response to the tumor was further enhanced by eribulin, but not by paclitaxel, as observed by the increase in activated CD4+ T-cells in both the spleen and the tumor draining lymph nodes of eribulin-treated tumored animals." (PMID 36497445, 2022). "In addition, CD8+ T cells can enhance antitumor activity to inhibit tumor cells through class I MHC and enhance immunotherapy by activating CD4+ T cells through class II MHC." (PMID 36230788, 2022). "With respect to the association between LC and the prognosis of patients with cancer, lymphocytes, which include CD4+ and CD8+ T cells, natural killer (NK) cells, NKT cells, gamma-delta T cells, and B cells, have been reported to play an important role in tumor immunity in the host." (PMID 35690739, 2022). "Interestingly, we also found that cGAMP increased IFN-γ production from tumor-infiltrating CD4 T cells as well as from MC38-OVA tumor-infiltrating OVA-specific CD4 T cells, suggesting that STING activation enhances CD4 T-cell effector functions in vivo." (PMID 35091453, 2022). "CD4+ T cells enhance the immune response in many ways, including facilitation of CD8+ T cells activation and proliferation, boosting the production of antibodies by B cells and direct anti-tumour cytotoxicity." (PMID 36138076, 2022). "DOX-JQ1@Gel reduced the expression of PD-L1 in tumor cells compared with tumors treated with empty hydrogels (Gel) and untreated tumors (UnTreated) as well as the expression of PD-1 in both CD8+ and CD4+ T cells." (PMID 35953828, 2022). "Consistent with their defect in Th2 polarization, Il4KO CD4+ T cells were not able to protect Tslptg TslprKO mice against PyMtOvatg TslprKO tumor growth." (PMID 35657353, 2022). "Thus, recent work showed that tumor resection in patients with oral and maxillofacial cancer is followed by a decrease in CD3+ CD4+ T lymphocytes and an increase in CD3+ CD8+ T lymphocytes." (PMID 35206956, 2022). "Several preclinical animal models have shown its critical role in tumour immunity, as only its depletion (by anti-CD25 depleting antibody or CD4 depletion in mice) or conversion into effector T cell can contribute to anti-tumour immunity, preventing tumour growth." (PMID 35406451, 2022). "They expressed, for the most part, TIGIT, but did not express CTLA-4, which was expressed by PD-1hiCD39+ CD4 T cells at the tumor site." (PMID 35954341, 2022). "CD4 depletion did not affect tumor growth and survival induced by Flt3L+NDV treatment; however, it should be noted that CD4-specific antibodies also deplete tumor-promoting regulatory T cells, potentially masking the effects mediated by CD4+ effector T cells." (PMID 36418317, 2022). "First, we performed global transcriptomics analysis (RNAseq) on different treatment groups (PBS, anti-PD-1 treatment, anti-PD-1 plus CD8+ depletion and anti-PD-1 plus CD4+ depletion) of the two selected syngeneic models, MC38 and Hepa1-6 tumors, for their contrasting tumor immunity." (PMID 35228603, 2022). "Finally, a single injection of cyclophosphamide, a drug able to induce ICD, can increase the Cxcl9, Cxcl10 and Cxcl11 expression within mastocytoma tumors (an effect dependent on CD4 T cells), thus allowing the recruitment of CD8 T cells and tumor regression." (PMID 36429101, 2022). "Though LT-α was found to induce the apoptosis of a wide range of tumor cells, its role in antitumor responses with CD4+ T cells has not been recognized." (PMID 35928827, 2022).
tumor (continued). "In contrast, a huge content of CD4, CD8, and CD19 lymphocytes and early mature and mature NK cells was found among the tumor-infiltrated immune cells after immunization of RtH-GD3P4 following the intensive scheme of administration, which correlates with the strong inhibition of the tumor growth." (PMID 35736195, 2022). "FOXP3-expressing Treg cells, mostly represented by CD4+ T cells that express CD25 (IL-2 receptor α-chain), are important for controlling self-tolerance and immune homeostasis, but also suppress antitumor immune responses and favor tumor progression." (PMID 35954312, 2022). "We next examined the levels of tumor regulatory T cells (Tregs, CD3+CD4+Foxp3+), which could suppress the antitumor immune responses of cytotoxic T lymphocytes and induce an immunosuppressive microenvironment." (PMID 35931666, 2022). "Tumor cells obtained after the treatment schedule were harvested, mechanically and enzymatically digested, and stained with anti-CD3, anti-CD8, anti-CD4, and anti-FOXP3 antibodies." (PMID 35991316, 2022). "Immunohistochemistry for HLA class I expression was performed using HLA-ABC in tissue microarrays and was analyzed in relation to clinicopathologic characteristics of tumors and infiltration of CD4+, CD8+, and FOXP3+ tumor-infiltrating lymphocyte (TIL) subsets and PD-L1+ immune cells." (PMID 36437379, 2022). "They demonstrated that CD8 depleting antibodies abolished tumor control, but there was no information regarding CD4+ T cells and their function while building immune response in PULSAR." (PMID 36275767, 2022). "In our study, LL-37 treatment reduced MDSC population and increased CD4+ and CD8+ T cell populations in the tumor microenvironment, and this shift may have contributed to the observed anti-tumor effects." (PMID 35935871, 2022). "Autophagosomes-induced CD4+ T cells in an IL-6- and IL-10-dependent manner suppress CD4+ and CD8+ effector T cell functions and induce IL-10-producing Breg cells via IL-6, IL-10 and IL-21, thereby promoting tumor growth and metastasis." (PMID 36365103, 2022). "Anti-DDR1-ECD monoclonal antibody resulted in fewer and shorter arrangements of collagen fibers at the tumor edge, which enhanced immune cell infiltration, increased the total number of infiltrating CD8+ and CD4+ T cells, and promoted interferon gamma (IFN-γ) production." (PMID 35935941, 2022). "CD4+ T cells and CD8+ T cells play an important role in killing tumor cells." (PMID 36386145, 2022). "Similarly, the increase in IFN-γ expression in CD4+ Tregs and CD8 TILs was significantly correlated with the ability of SC79 to limit tumor growth." (PMID 36323740, 2022). "The immunophenoscore (IPS) is a tumor immunogenicity index calculated based on four representative immune cells: activated CD4+ T cells, activated CD8+ T cells, effector memory CD4+ T cells, and MDSCs, which is positively correlated with the response rate to immune checkpoint inhibitors." (PMID 36091041, 2022). "Besides, we evaluated the therapeutic effects of combined cilengitide and anti-PD1 antibody in a murine melanoma model, including characterizing CD4+ and CD8+ tumor infiltrating lymphocytes (TILs) in both subcutaneous tumors and spleens of mice." (PMID 35142593, 2022). "The increased expression of DAMPs and tumor antigens reprogramed the immunosuppressive TME in the HCC, embodied in the upregulation of DCs, NK cells, M1-like TAMs, CD8+ cytotoxic/memory T cells, and CD4+ helper/memory T cells." (PMID 36615387, 2022). "Analysis of tumor immune infiltration showed the elevated expression levels of IGF2BP3, DPCR1, HOXD10, TRIM7, and ZIC5 tended to be correlated with the increased tumor infiltrating B cells, CD8+ T cells, CD4+ T cells, and APCs including macrophages and DCs in COAD patients." (PMID 35593226, 2022).
tumor (continued). "Most CD4+ T cells effectively improve both the memory and cytotoxic functions of CD8+ cytotoxic T lymphocytes (CTLs) and help CTLs to restrain tumor cells from immune escape through the release of multiple favorable cytokines in tumor microenvironment." (PMID 35523765, 2022). "Accordingly, a combination of high-dose Vit-C (4 g/kg) with anti-CTLA-4 (200 μg) and anti-PD-1 (250 μg) antibodies resulted in significant tumor impairment and remission via the infiltration and activation of anti-cancer adaptive immunity (CD8 T and CD4 T cells), especially CD8 T cells." (PMID 35745630, 2022). "Altogether, these data suggest that the presence of MOPC315.BM-derived EV leads to suppression of anti-tumor immunity by CD4+ T cells, even in the absence of MM clonal cells." (PMID 35874665, 2022). "Moreover, TGF-β from tumor effusions mediates the inhibition of mitochondrial respiration and the generation of IFN-γ in human CD4+ T subsets." (PMID 35720407, 2022). "Furthermore, the TME prevents immune cells, such as CD4+ and CD8+ T cells, from infiltrating the tumor site." (PMID 35832074, 2022). "Moreover, infiltration of CD3+ T cells into mouse tumor tissues treated with either PF543 or anti‐PD‐1 antibody was enhanced compared to untreated tumor tissues as detected by IHC staining of CD3, CD4, and CD8 markers." (PMID 35289120, 2022). "Furthermore, tumor microenvironment analysis suggests that high POLD2 expression inhibits infiltration of CD8+ T cells and CD4+ memory T cells." (PMID 36081989, 2022). "Furthermore, morphine treatment reduced the LDH release and the percentage of CD8+ T cells, and increased the ratio of CD4+/CD8+ T cells and tumor weight." (PMID 36476246, 2022). "At the tumor center, the number of neutrophils (TAN-TC) was weak and positively correlated only with the number of CD3-TC, while the number of neutrophils in the invasive front (TAN-IF) was weak and positively correlated only with the number of CD4-IF." (PMID 36526699, 2022). "Although CD8-predominant AITL has histological features similar to those of common AITL, it has a lower TIL-B proportion, an inverted CD4+/CD8+ TIL-Ts ratio, deterioration of TR and IGH repertoire metrics, and altered gene expression profiles, indicating the anti-tumor immunity impairment in TME." (PMID 36325319, 2022). "Histopathological (granulomas, perineural inflammation, etc.)and immunological features [e.g. B cells/plasma cells (CD20/CD138) and T cells (CD3,CD4,CD8)] were scored and correlated with durable tumor response [i.e. complete response (CR) persisting beyond 6 months after treatment]." (PMID 35446267, 2022). "The FACS analysis of tumor mass revealed that while tumor-infiltrating T-cell populations, including CD3+, CD3+/CD4+, CD3+/CD8+ cells were significantly lower upon MLN4924 treatment, the combination with MEK inhibitor or anti-PD-L1 antibody restored the cytotoxic T-cell population." (PMID 36192389, 2022). "Preclinical studies reveal that dual checkpoint blockade with anti-PD1 and anti-CTLA4 decreases replacement of T effector cells with T regulatory cells, enhances dendritic cell activation, and increases activation of tumor-infiltrating cytotoxic CD8+ and CD4+ T cells." (PMID 35214172, 2022). "The limited overlap between the CD4+ and CD8+ antitumor responses suggest that they are complementary and might help overcome tumor heterogeneity." (PMID 35439168, 2022). "Therefore, this study confirms the potential use of increased IFN‐γ levels posttreatment as a correlate of response to IL‐12 gene therapy and the potential importance of increased CD4+ and TIA‐1+ CD8+ T cell tumor infiltration." (PMID 35790025, 2022). "Moreover, in vivo experimental results revealed that IM@ZP enhanced photothermal immunotherapy as shown by promoted tumor infiltrating CD8 + and CD4 + T cells and NK cells, and inhibited tumor growth and lung metastasis." (PMID 35236356, 2022).